LDHAP7 (lactate dehydrogenase A pseudogene 7)
Synonyms: formerly LDHAL7
Gene: Processed pseudogene on chromosome 2 (84,777,259 to 84,778,223, reverse strand). Ensembl gene ENSG00000235847.
Diseases named in the same sentence as LDHAP7 in open-access papers:
LDHAP7 is named in the same sentence as 1 disease in open-access papers, as found by Europe PMC text mining. Sharing a sentence is not in itself a finding about the gene and the disease. The quoted sentences say what the papers report.
tumor (1 paper, 2022). "Compared to HPV negative, patients with HPV positive had significantly higher expressions of oncogene pseudogenes (SDHAP1, SDHAP3, DDX12P, CLUHP3, and RRN3P3), but there was no prominent difference in the expressions of tumor-suppressor pseudogenes (PDIA3P1, LDHAP4, LDHAP7, EEF1A1P6, and EEF1A1P11)." (PMID 36438489, 2022).